B2M (beta-2-microglobulin)
Diseases named in the same sentence as B2M in open-access papers (continued):
Sharing a sentence is not in itself a finding about the gene and the disease.
melanoma (continued). "In the Yummer B2M KO melanomas, with relatively lesser TAM infiltration, compared to MC38 B2M KO tumors, a robust induction of CCL2 is observed along with a significant increase in TAM numbers." (PMID 40560386, 2025). "Intriguingly, this PD1res melanoma had a massive infiltration of CD3+ T cells and had predominantly B2M positive melanoma cells in contrast to most other PD1res melanomas." (PMID 38594286, 2024). "We then mimicked the melanoma cell states identified by the Visium sequencing using mIF antibodies for SOX10, MITF, B2M and NGFR." (PMID 38594286, 2024). "The B2M-altered SCC13-0156 and SMU-092 melanoma cell lines and matched tumor dissociates also expressed low levels of MHC-II." (PMID 36934113, 2023). "Our results display that B2M and YWHAZ represent the most optimal reference genes to reliably quantify hypoxia-inducible CYGB expression in melanoma cell lines." (PMID 34035373, 2021). "Sade-Feldman and colleagues analyzed escape lesions from five melanoma patients treated with Ipilimumab (anti-CTLA4 Abs) and found LOH in B2M in 29.4% of the cases." (PMID 34680201, 2021). "Indeed they found by whole genome sequencing, that two of four melanoma metastatic patients analyzed acquired loss of function mutation in the genes coding for JAK1/2, and the third patient presented a truncated mutation in the gene coding for beta-2-microglobulin (B2M)." (PMID 34571790, 2021). "Another study performed on melanoma patients in stage II and III reported the combination of serum TNF-alpha, soluble IL-2 receptor and beta-2 microglobulin to be strong predictive markers of relapse in melanoma before treatment." (PMID 32309563, 2015). "Lack of TIL reactivity in a beta-2-microglobulin (B2M)-ablated canine melanoma sample confirmed that recognition was major histocompatibility complex (MHC) class I-dependent." (PMID 42212155, 2026). "Next, we obtained multiple human malignant melanoma and colon adenocarcinoma tissue samples and stained for 5hmC as a marker for TET2 activity and for the key MHC I antigen-presenting genes TAP1, TAPBP, and B2M." (PMID 39388288, 2024). "Our work describes that de-differentiated melanoma cells lacking B2M expression are frequently observed in anti-PD1 resistant melanomas." (PMID 38594286, 2024). "Downregulation of B2M and HLA was observed in non-responder melanomas, although these were not significant." (PMID 36248850, 2022). "Tail vein injections of WT and B2m-/- B16 melanoma cells did not alter the CD11b+ mature NK cell dominance, but it significantly decreased IVpos DP population and likely led to their conversion into CD11b+CD27- NK cells in the circulation." (PMID 36733396, 2022). "The study found that in mice lacking NK cells, the number of B2M-depleted melanoma cells was significantly increased compared with B2M +/+ cells." (PMID 36046045, 2022). "The first patient presented with a recurrent malignant melanoma and no genetic alterations in the B2M gene." (PMID 36615128, 2022). "Similar to anti-CTLA4-treated patient cohort, NLRC5 and HLA-B was reduced in non-responders, along with a similar trend for B2M in anti-PD1-treated melanoma patients." (PMID 33547395, 2021). "Certain genetic mutations in melanoma, including JAK1, JAK2, B2M and PTEN, etc., correlate with negative treatment response of PD-1 blockade therapy, while BRCA2 mutations were reported enriched in melanomas responsive to this treatment." (PMID 32333081, 2020). "We have data demonstrating that HLA-I loss caused by B2M mutations is not very common in NSCLC in contrast to what has been reported in colorectal cancer and melanoma." (PMID 29423109, 2018). "Consistently, another RNA-seq dataset from patients with advanced melanoma treated with ipilimumab followed by nivolumab revealed an increase in USP22 transcripts in nonresponders compared with responders, which were inversely correlated with B2M transcript levels." (PMID 41252204, 2025).
melanoma (continued). "The immune and inflammatory response node contained 99 proteins and genes directly involved in the immune response such as interleukins and chemokines; T lymphocyte markers such as CD96, TLR8, CD80; or CCR5, beta-2-microglobulin (B2M) or absent in melanoma 2 (AIM2)." (PMID 37686682, 2023). "Indeed, melanoma patients with low or absent B2M/MHCI expression but increased MHCII expression demonstrated higher responses to ICB." (PMID 37371815, 2023). "Recently, patients with melanoma who did not respond to anti-PD1 therapy were shown to carry mutations in pathways involved in IFN-receptor signaling and in antigen presentation, such as B2M." (PMID 37478172, 2023). "Next, the three cancer cell lines: Renca‐RCC, B16‐F10‐Melanoma (both “hot tumors”) cells and RM1‐Prostate cancer cells (“cold tumor”) were used to confirm whether the αKG could induce histone demethylation and regulate the expression of B2M." (PMID 37526345, 2023). "In addition to well-established IFNγ target genes such as CD274, IRF1, and B2M, three members of the PARP family—PARP9, −12 and −14—were consistently upregulated in all cell models as well as in IFNGhigh patient melanoma (comparing top 15% by IFNG expression to lowest 15% in the TCGA SKCM dataset)." (PMID 37752135, 2023). "We provide further evidence that epigenetic changes in the TME of melanoma tumors have a direct impact on B2M and an indirect impact on CD1D gene expression (through SPI1) but not on CD1B and FCGRT expression in melanoma patients from the TCGA dataset." (PMID 37077920, 2023). "Genetic alterations in antigen presentation (B2M, HLA-A) and IFNγ signaling (IFNGR, STAT1 and JAK1/2) in non-responding melanoma patients are uncommon, and not restricted to non-responding patients." (PMID 32312968, 2020). "In two independent cohorts of melanoma patients treated with anti-CTLA4 and anti-PD1, respectively, we find that B2M LOH is enriched threefold in non-responders (~30%) compared to responders (~10%) and associated with poorer overall survival." (PMID 29070816, 2017). "Evidence suggests a transcriptional regulation of the antigen presentation machinery, as genetic alterations in antigen presentation (B2M, HLA-A) and IFNγ signaling (IFNGR, STAT1 and JAK1/2) remain infrequent in melanomas and are not restricted to non-responding patients." (PMID 35432344, 2022).
multiple myeloma (47 papers, 1980 to 2025). "Studies have indicated elevated B2M expression in prostate cancer cells, linking it to metastatic tendencies, and surges in serum B2M levels in multiple myeloma patients have been associated with enhanced angiogenesis and myelosuppression." (PMID 38395751, 2024). "Autoimmune, neoplastic, and infectious diseases, such as multiple myeloma, lymphoma, and Sjogren’s syndrome have also reported to associate with increased plasma levels of B2M." (PMID 28249620, 2017). "As our myeloma staging systems have evolved, the role of beta-2 microglobulin ought to be questioned." (PMID 40973877, 2025). "MM, multiple myeloma; df, degrees of freedom; P, Probability; Hb, hemoglobin; Cr, creatinine; Ca, calcium; β2-MG, serum beta-2-microglobulin; ALB, albumin; LDH, lactate dehydrogenase." (PMID 40259951, 2025). "Beta-2 microglobulin is a well-known prognostic factor in multiple myelomas and some hematological malignancies." (PMID 40565831, 2025). "When the kidney function is normal, the beta-2 microglobulin seems to reflect the entire mass of myeloma cells and, in our study population, as expected, it is negatively related to albumin levels (p < 0.001)." (PMID 38310176, 2024). "To compensate for this, we tried to select ATTR-CM exclusively by broadly including cardiac amyloidosis and excluding patients with other cardiac amyloidoses such as AL amyloidosis, AA amyloidosis, and Beta-2-microglobulin amyloidosis." (PMID 35840997, 2022). "Plenty of researches have shown that the concentration of B2M in serum or urine raised in diverse diseases, such as breast cancer, prostate cancer, lung cancer, renal cancer, multiple myeloma, and especially non-Hodgkin's lymphoma." (PMID 33658560, 2021). "The International Staging System, which is based on serum beta-2 microglobulin and albumin levels, is the most widely adopted in multiple myeloma and is also correlated with the prognosis of the disease." (PMID 34069672, 2021). "Biomarkers primarily in the blood (e.g., IgG for myeloma) but occasionally in the urine (e.g., Beta-2 microglobulin for leukaemia) or in the cerebrospinal fluid (e.g., fibrin for bladder cancer) can assist in diagnosis and monitoring." (PMID 35055975, 2021). "Specifically, measurement of serum beta-2 microglobulin is essential for baseline work up of multiple myeloma and follicular lymphoma patients." (PMID 27764777, 2016). "The main clinical utility for serum beta-2-microglobulin is in the workup of multiple myeloma and this would be an unusual order in the obstetric population." (PMID 25880934, 2015). "Beta-2 microglobulin is commonly elevated in lymphoid malignancies including multiple myeloma, showing a strong correlation to tumor burden." (PMID 25706753, 2015). "These values were compared with the presence of anemia, renal dysfunction, and bone lesions as myeloma related clinical manifestations and with serum beta-2 microglobulin and Durie-Salmon clinical stage as prognosticators related to tumor mass." (PMID 24995304, 2014). "Serum beta 2 microglobulin would appear to be a key measurement for assessing the prognosis and response to treatment in patients with myelomatosis." (PMID 3893505, 1985). "Beta-2 microglobulin is an established prognostic marker in AL amyloidosis." (PMID 41035599, 2025). "Additionally, beta-2 microglobulin was markedly elevated (up to 8.45 mg/L; normal range: 0.97-2.00 mg/L), indicating severe tumor burden and poor prognosis in AL amyloidosis." (PMID 41035599, 2025). "In a multivariable proportional hazards Cox regression analysis adjusted according to demographic and clinical factors, we selected age, gender, eGFR,HB,LDH,RI, albumin, serum/urinary lambda or kappa light chains, serum beta 2-microglobulin, and anti-myeloma therapy regimen as confounding factors." (PMID 35756671, 2022). "Moreover, high concentrations of B2M suppress the proliferation of primary tumor cells and myeloma cell lines and induce apoptosis and cell‐cycle arrest." (PMID 33960680, 2021).
multiple myeloma (continued). "Serum B2-M level and the frequency of BM myeloma PCs were selected as markers of tumor burden." (PMID 33257767, 2020). "Serum B2M level and the morphology of myeloma cells are reliable prognostic factors in MM." (PMID 31042345, 2019). "The international staging system (ISS), based on serum beta-2 microglobulin and albumin, is used to predict survival in multiple myeloma, but its prognostic significance in diffuse large B-cell lymphoma (DLBCL) remains unknown." (PMID 29051524, 2017). "The levels of serum beta 2 microglobulin, blood urea concentration, serum creatinine, haemoglobin and performance status have been measured in 476 patients in the Medical Research Council's 4th trial for myelomatosis." (PMID 3893505, 1985). "Serum beta 2-microglobulin (beta 2-m) is frequently increased in patients with myelomatosis." (PMID 6185132, 1983). "Additionally, B2M monoclonal antibodies have been shown to exhibit therapeutic efficacy and low toxicity in human‐like myeloma mouse models, which express mature and functional human B2M in murine organs and present high levels of circulating human B2M derived from human myeloma cells." (PMID 33960680, 2021). "Moreover, the levels of biological markers, including albumin, creatinine, and hemoglobin (Hb) and myeloma status including lactate dehydrogenase, beta 2‐microglobulin (B2M), ISS, and R‐ISS were relatively lower in the patients with social frailty than those without social frailty." (PMID 35847687, 2020). "Gossypol also upregulates expression of proteins associated with antigen presenting pathways including HLA classes I and II histocompatibility antigens and beta-2-microglobulin that may elicit immune responses and be developed into a new therapeutic approach for multiple myeloma treatment." (PMID 25197664, 2014). "Moreover, we correlated them with markers of myeloma activity, such as serum levels of IL-6, IL-10, IL-15, beta-2 microglobulin (B2M), and C-reactive protein (CRP), as well as with plasma cells' infiltration and Ki-67-PI in the bone marrow, both in diagnosis and after effective therapy." (PMID 23936794, 2013). "Research has shown that B2M was high expression in prostate cancer cells and increased B2M was related to distance metastasis, and increased serum levels of B2M and FLT3-L in patients with multiple myeloma may be associated with increased angiogenesis and myelosuppression." (PMID 35321689, 2022). "Serum B2-M level and CD45dimCD38+CD138+CD56+CD19−CD117+CD27−CD81− BM myeloma PCs were selected as markers of tumor burden and were assessed in 48 and 38 treated MM patients, respectively." (PMID 33257767, 2020). "Recognizing this, the International Myeloma Working Group (IMWG) accumulated data from 10 750 patients across 17 countries and devised the ISS which combined 2 simple prognostic values, albumin and beta-2 microglobulin." (PMID 40973877, 2025). "Specifically, in a cohort of 190 newly diagnosed multiple myeloma patients, we have examined the behaviour of RDW and its trend in relation to the ISS stage and other prognostic factors, such as albumin, beta-2 microglobulin, LDH and bone marrow plasma cell infiltration." (PMID 38310176, 2024). "Neither the paraprotein subtype or burden, beta-2-microglobulin level or International Myeloma Working Group (IMWG) international staging system (ISS) status at diagnosis were predictive of VTE." (PMID 34441832, 2021). "Urinary psi excretion is independent of the main indices of tumour activity in myelomatosis (serum paraprotein, serum beta 2-microglobulin, serum creatinine and urinary light chain production)." (PMID 3907686, 1985). "Patients with LSV had a lower SSR and a negative correlation between the SSR and beta-2 microglobulin or BMPC was also identified, suggesting that SSR inversely reflected the myeloma burden." (PMID 34907317, 2021). "BCAR3 (P = 5.17E−03) is a prognostic factor independent of B2M, MRI, and BMPC in myeloma patients." (PMID 30563570, 2018).
amyloidosis (37 papers, 2007 to 2025). A disorder characterized by the localized or diffuse accumulation of amyloid protein in various anatomic sites. "B2M, which forms insoluble fibrils associated with dialysis-related amyloidosis, exhibited comparable fibril-forming properties in dental plaque." (PMID 41334357, 2025). "High levels of B2M can result in the formation of amyloid-like deposits in the brain, which can cause neurodegenerative diseases such as dialysis-related amyloidosis." (PMID 40559873, 2025). "Concerning its amyloidogenic nature under pathological conditions, B2M is the main cause of dialysis-associated amyloidosis, a property that is specific for human B2M." (PMID 33092477, 2020). "EU/3/12/955) and of β2-microglobulin amyloidosis (Treatment of systemic amyloidosis caused by beta-2 microglobulin." (PMID 31546787, 2019). "This study has further consolidated the role of B2M in two different types of amyloidosis: one occurring during dialysis-related amyloidosis due to elevated levels of B2M and the other occurring due to mutations causing the B2M to become more aggregation prone and amyloidogenic." (PMID 38152117, 2024). "These genes, Thy1, Gfap, Tyrobp, Ctsd, Cst7, C1qb, Lyz2, Ctss, Trem2, Mpeg1, Hexb, Cd68, C1qb, C1qa, Ctsz, Grn, Laptm5, B2m, C1qc, Hexa, and Serpina3n, were increased in the 7-month-old 5XFAD model in the cortex and associated with amyloid plaque image patterns." (PMID 38036733, 2023). "To investigate these mechanisms, we used a combination of NMR spectroscopy and molecular dynamics simulations to compare the native state dynamics of Beta-2 microglobulin (β2m), whose aggregation is associated with dialysis-related amyloidosis, and its aggregation-resistant mutant W60G." (PMID 27150430, 2016). "Beta 2-microglobulin associated amyloidosis: A vanishing complication of long-term hemodialysis?" (PMID 23504584, 2013). "In a clinical trial comparing medium-cutoff membrane dialysis with traditional low-flux hemodialysis, it was found that medium-cutoff membrane dialysis could achieve a higher clearance rate for B2M, which is beneficial for preventing dialysis-related amyloidosis caused by the accumulation of B2M." (PMID 40559873, 2025). "Notably, the PTM of B2M, particularly glycation, may yield amyloid fibrils that are deposited in patients with hemodialysis-associated amyloidosis." (PMID 34199259, 2021). "MIC-M2 featured hub genes SORL1 and B2M, both implicated in a variety of AD-related processes such as trafficking of APP and resultant amyloidosis in AD." (PMID 38913039, 2024). "Beta-2 Microglobulin amyloidosis: Beta-2-Microglobulin amyloidosis (ß2MA) is a disabling condition that can affect long-term hemodialysis patients." (PMID 39458115, 2024). "She reported fatigue, acroparesthesias (attributed to beta-2-microglobulin amyloidosis), abdominal pain, and constipation." (PMID 39337589, 2024). "CRF leads to reduced renal excretion of B2M resulting in chronically elevated plasma concentrations of 50–100 μg/mL, in which the amyloid state will commonly arise." (PMID 37509158, 2023). "In CRF, the high concentration of circulating B2M often results in amyloid deposition in a condition known as dialysis-related amyloidosis (DRA)." (PMID 37509158, 2023). "B2M-related amyloidosis has one striking feature that is primarily limited to the skeletal muscular system." (PMID 34199259, 2021). "Lysozyme (ALys amyloidosis) and beta-2-microglobulin (DRA), as proteins with significantly different secondary and tertiary structures and stability, were chosen by us as target proteins." (PMID 33081200, 2020). "There can also be amyloidosis related to the overproduction of β2 microglobulin (B2M amyloidosis), a free protein with an antibacterial activity that is a light chain of the major histocompatibility complex protein." (PMID 33123145, 2020). "Due to its ability to form amyloid fibrils B2M is responsible for the development of hemodialysis related amyloidosis." (PMID 33092477, 2020).